LINC01506 (long independently transcribed non-coding RNA 1506)
Gene: Long non-coding RNA gene on chromosome 9 (68,509,620 to 68,634,901, reverse strand). Ensembl gene ENSG00000234506.
Diseases named in the same sentence as LINC01506 in open-access papers:
LINC01506 is named in the same sentence as 1 disease in open-access papers, as found by Europe PMC text mining. Sharing a sentence is not in itself a finding about the gene and the disease. The quoted sentences say what the papers report.
tumor (1 paper, 2023). "Of the 46 PRLs, 38 showed significant differences between tumor and normal tissues, while AC006369.1, AC007038.1, AC116049.1, AL008729.1, AL031705.1, AL138831.3, LINC01506 and SSBP3-AS1 did not." (PMID 36917093, 2023).